RNU6-1209P (RNA, U6 small nuclear 1209, pseudogene)
Gene: Small nuclear RNA gene on chromosome 8 (95,055,214 to 95,055,320, forward strand). Ensembl gene ENSG00000200525.
Homologues: Orthologues: chimpanzee U6 (98% identical), macaque U6 (90% identical). Paralogues in human: RNU6-797P (93% identical), RNU6-742P (92% identical), RNU6-560P (91% identical), RNU6-1145P (89% identical), RNU6-1309P (89% identical), RNU6-183P (89% identical), RNU6-744P (89% identical), RNU6-83P (89% identical), RNU6-1175P (88% identical), RNU6-11P (88% identical), RNU6-1316P (88% identical), RNU6-151P (88% identical), and 1287 more.